PPARG (peroxisome proliferator activated receptor gamma)
Diseases named in the same sentence as PPARG in open-access papers (continued):
Sharing a sentence is not in itself a finding about the gene and the disease.
tumor (continued). "Therefore, PPARγ antagonist treatment can resensitize tumor cells to anti-PD-L1 treatment." (PMID 38397901, 2024). "However, the role of PPARγ in tumor immune microenvironment is still controversial." (PMID 38397426, 2024). "Interestingly, PPARγ activation may have pro-tumor effects on cells of the tumor microenvironment, especially myeloid cells." (PMID 38397426, 2024). "PPARγ is key in this interaction between ILC2s and cancer cells: it supports the pro-tumoural functions of ILC2s, and this function might be conserved across different IL-33-dependent tumours." (PMID 38662248, 2024). "Proteins associated with tumor progression or a bad prognosis such as WNT5A, MMP13, MMP3, telomerase, and NOTCH3 were upregulated while proteins associated with immune cell infiltration or pathway inhibitors/tumor suppressors such as FRZB, CD177, PPARG, and HRASLS2 were downregulated." (PMID 38504345, 2024). "PPARγ-mediated lipid metabolism may hinder immune response and facilitate tumor growth." (PMID 38264667, 2023). "In summary, PPARγ activity in healthy tissues places several stromal cell types in an antitumorigenic state, directly inhibiting EC proliferation, maintaining adipocyte differentiation, and suppressing the transition of pericytes into tumor-supportive myofibroblasts." (PMID 37816052, 2023). "Thus, higher expression of GDE7 could suppress PPARγ via increased cPA levels and potentially accelerate tumor progression." (PMID 37193762, 2023). "Our findings suggest that synthetic agonists may demonstrate more significant therapeutic benefits in cancer-prone individuals at high risk of developing cancer prior to a tipping point that leads to the irreversible repression of PPARγ and the development of a supportive tumor microenvironment." (PMID 37816052, 2023). "Therefore, we next wanted to determine whether PPARγ activity in pericytes could limit their tumor growth-promoting potential." (PMID 37816052, 2023). "Therefore, by modulating the expression or activity of PPARG, it may be possible to interfere with these pathways and inhibit tumor growth and metastasis." (PMID 37334066, 2023). "In particular, evaluating the different PPARγ positivity degrees among vehicle and melatonin cryopass-laser, we observed that this downstream protein is more expressed in the nuclei of vehicle-treated tumor cells, with a significant difference compared to melatonin-treated tumors." (PMID 37894275, 2023). "Tumor-associated myeloid cells exhibited higher transcriptional expression of molecules linked to the “find me” (G2A), “eat me” (CD93, TIM1, SCARF1, SLC2A1, GAS6, TREM2, AXL, C1QA), and downstream processing (NR1H3, ATG7, PPARG, ABCA1, PPARD, DOCK180) phases of efferocytosis." (PMID 36439171, 2022). "The conundrum of PPARγ in colon carcinogenesis suggests that early treatment with the PPARγ agonists before the first step of carcinogenesis occurs may prevent tumor formation, but that activation of PPARγ after tumor initiation, as is the case in the APCMin mice, may promote cancer." (PMID 35163356, 2022). "Therefore, the impact of rs1801282 SNV on the expression of the PPARγ may vary by tumor type and race." (PMID 36587194, 2022). "Similarly, the cytotoxicity of DHA on many tumor cells is related to the activation of PPARγ." (PMID 36286423, 2022). "Therefore, circRFWD3 and PPARγ could serve as tumor promoters, and their high expression might predict a poor prognosis for HNSCC patients." (PMID 35690612, 2022). "Additionally, our results show that the expression of the phosphorylated variant of PPARγ (pS112), but not the total protein variant, was significantly upregulated in cold tumor samples, whereas CD8 expression displayed the opposite trend." (PMID 36139700, 2022).
tumor (continued). "The stimulatory activity of PPARγ agonists changes phenotypes and functions of both, malignant and non-malignant cells and their respective ‘communication protocol’ due to the ubiquitous, but differential expression of PPARγ in all cell compartments of the tumor tissue." (PMID 35814409, 2022). "Furthermore, mice implanted with either the shControl MHCC-97H cells or the MHCC-97H cells with simultaneous USP22 knockdown and PPARγ overexpression showed similar tumor growth rates, whereas mice bearing the USP22-knockdown MHCC-97H cells showed markedly inhibited tumorigenesis." (PMID 35449157, 2022). "On the one hand, POX/PRODH might act as a tumor survival factor through AMPK kinase or peroxisome proliferator-activated receptors-γ (PPARγ) when induced under stress conditions, e.g., in nutrient or oxygen deprivation or stimulation by oxidized lipids (oxLDL)." (PMID 35454935, 2022). "The independence of COX-2 and PPARγ as a predictive factor for overall survival from other clinical pathological factors was tested by a cox regression analysis (* p = 0.001) in comparison to tumor stage, nodal state, grading, FIGO- classification, and p16-state." (PMID 33802010, 2021). "Interestingly, peroxisome proliferator-activated receptors (PPARs) have also emerged as potential therapeutic targets for modulating tumor growth, and genistein at a concentration of ≥5 μM has been documented to promote apoptosis in tumor cells via targeting PPARγ signaling cascade." (PMID 34567112, 2021). "In addition, some researchers mentioned that PPARG can inhibit tumor progression." (PMID 34567087, 2021). "GPR132 expression is reduced by the activation of peroxisome proliferator-activated receptor γ (PPARγ) in tumor-associated macrophages (TAMs); moreover, breast tumor cells produce lactate which activates GPR132 in TAMs, promoting macrophage M2 activation and tumor growth." (PMID 35095895, 2021). "Factors affecting drug efficacy could include compound-specific effects, the necessity of Pparγ activation or other targets, the tumor stage at the time of drug exposure, the age of the patient, and finally the influence of TZDs on cancer cell paracrine activity." (PMID 34195082, 2021). "In our tumor model, we found that taxifolin treatment led to reduced expression of genes encoding fatty acid synthesis-related proteins C/EBPa, PPARγ, FABP4, and FAS, suggesting that tumor cell lipid synthesis was reduced and that this may have contributed to the inhibition of tumor growth." (PMID 34462635, 2021). "Furthermore, the pro-apoptotic and anti-proliferative effect in tumor cell lines with PPARγ agonists could be proven in some studies." (PMID 33802010, 2021). "In this study, we have demonstrated that upregulation of PPARγ expression specifically in MES GSCs may serve as a molecular signature representing pathologic diagnosis biomarkers as well as therapeutic targets for that particular tumor subtype." (PMID 32280134, 2020). "Given the key role played by PPARγ in the crosstalk between cancer cells and TAMs in tumor progression, its activation via endogenous or synthetic ligands may lead to novel strategies that target both epithelial neoplastic cells and the tumor microenvironment." (PMID 31936729, 2020). "However, some studies have found that activation of PPARγ can promote tumor development." (PMID 33029112, 2020). "Hence, these genes might serve as molecular targets to restrict oncogenic (i.e. ATIC, BZW2) and lipogenic (i.e. CD36, PPARγ), but promote tumor suppressive (i.e. TAGLN2) activity to treat human HCC." (PMID 32559205, 2020). "The crucial role of PPARγ emerges from the ability of this activated receptor to mediate the energy metabolism of adipocytes suggesting that the regulation of adipocyte energy stores which are sensitive to PPARγ could reveal new anti-tumor therapeutic possibilities." (PMID 33352766, 2020).
tumor (continued). "Likewise, cancer-associated mutations in combination with various endogenous ligands might complicate PPARγ-dependent tumor microenvironment for different cancers, which should be further elucidated." (PMID 33266062, 2020). "Additionally, PPARγ functions as a tumor suppressor and its expression is lost in many cancers." (PMID 31620124, 2019). "Recent evidence suggests that PPARγ agonists may promote anti-tumor immunity." (PMID 31212694, 2019). "In addition to potential direct effects on tumor cells, PPARγ agonists have also been shown to suppress cellular signaling pathways that are associated with the production of many inflammatory cytokines and chemokines that can recruit and activate cells of the immune system." (PMID 31212694, 2019). "Importantly, we observed that PPARγ activation in the tumor tissues was in line with the expression of the target gene PTEN, but inversely correlated with the activation of Akt, as indicated by the phosphorylation of Akt (Ser473) and its downstream FoxO1 (Ser256) and Bcl2 (Ser70)." (PMID 30845932, 2019). "Also, DHA has been reported to generate a tumor suppressive effect via PPARγ." (PMID 31620124, 2019). "Interestingly, peroxisome proliferator-activated receptors (PPARs) have also surfaced as potential therapeutic targets of interest for modulating tumor growth, and genistein has been documented to induce apoptosis in tumor cells via targeting PPARγ signaling cascade." (PMID 31866857, 2019). "Thus, given the known role of PPARγ in regulating inflammatory signaling, this suggests that PPARγ activation could also indirectly effect tumor growth and development through its immunomodulatory activity." (PMID 31212694, 2019). "PPARγ agonists, by decreasing the WNT/β-catenin pathway, may be utilized in association with other drugs, including inhibitors of tyrosine kinases, Akt, and MAPK cascades, to maximize the anti-tumor and pro-differentiating effect." (PMID 31311204, 2019). "Given the ability of PPARγ signaling to alter the balance of T-cells and myeloid cells in lung tissue, we also examined whether PPARγ altered the balance of these important immune cells in the anti-tumor response." (PMID 31212694, 2019). "Thus, PPARγ agonists may act to suppress tumor development or growth through multiple mechanisms, with direct effects on tumor growth as well as indirect effects mediated through the immune system." (PMID 31212694, 2019). "Researchers has found that after being activated by ligand, PPARγ can induce tumor cell differentiation, repress their proliferation, promote their apoptosis, and concomitantly reduce neoplastic angiogenesis, which eventually halts the tumor growth, proliferation, infiltration, and metastasis." (PMID 29483923, 2018). "Moreover, the activation of PPARγ can reduce the invasion ability of tumor cells." (PMID 29642873, 2018). "Pioglitazone may activate PPARγ, which is suggested to be a tumor suppressor in prostate cancer." (PMID 30546308, 2018). "Interestingly, PPARγ has been found to increase Dlc1 expression to inhibit tumor growth, and because PPARγ is a master regulator of adipogenic differentiation, we ask whether PPARγ can also regulate Dlc1 level in adipocytes and affect differentiation." (PMID 28358928, 2017). "Therefore, targeting the caspase-1/PPARγ/MCAD pathway might be a promising therapeutic approach to prevent tumor progression." (PMID 28974683, 2017).
tumor (continued). "Many studies have revealed that PPARγ acts as a tumor inhibitor, because it is mainly exposed in prostate, breast, and colonic epithelium and the appearance of cultured cancer cell lines suppositious of these tissue types with ligands of PPARγ restrain cellular proliferation." (PMID 28460464, 2017). "Finally, modulating MCAD activity in TAMs through treatment with caspase-1 inhibitors or genetic manipulation suppressed primary tumor growth in in vivo mouse models, thus supporting potential clinical applications for targeting the caspase-1/PPARγ/MCAD pathway in TAM differentiation." (PMID 28974683, 2017). "Interestingly, within the tumor we detected small undifferentiated cells that also expressed PPARG." (PMID 28275008, 2017). "Moreover, these PPARγ agonists inhibited tumor cell proliferation and angiogenesis in vivo." (PMID 27699500, 2017). "In addition, overexpression or silence of PPARγ suggests that it indeed inhibits tumor growth." (PMID 28948004, 2017). "Thus, the authors speculated that the downstream signaling of PPARγ in tumor cells would be specifically dysregulated by the FUS-DDIT3 transgene even at higher PPARγ levels." (PMID 27401457, 2016). "Thus, the identification of the MEK/ERK/PPARγ/PFKB4 axis regulating glycolysis elicits a potentially new approach to targeting a tumour-specific metabolic pathway and understanding the mechanisms of hepatocarcinogenesis, its detection, therapeutic intervention, and prevention." (PMID 27769068, 2016). "Similarly, PPARγ may affect many genes in macrophage, and targets other than Gpr132 may also contribute to the anti-tumor effects of PPARγ." (PMID 27692066, 2016). "Importantly, this rosiglitazone effect was macrophage-PPARγ-dependent because tumor cell proliferation was increased equally when co-cultured with PPARγ-deficient macrophages regardless of rosiglitazone or vehicle treatment." (PMID 27692066, 2016). "Thus, it is yet unknown which molecular mechanisms influence PPARγ expression on MLS tumor malignancy." (PMID 27401457, 2016). "However, it remains enigmatic whether and how macrophage contributes to PPARγ tumor-suppressive functions." (PMID 27692066, 2016). "However, it is not fully understood how PPARγ and TZDs suppress tumor development." (PMID 27692066, 2016). "Consequently, tumor growth is inhibited when the macrophage Gpr132 level is low by either Gpr132 deletion/inhibition or PPARγ activation via rosiglitazone; whereas tumor growth is exacerbated when the macrophage Gpr132 level is high as the result of macrophage PPARγ deficiency." (PMID 27692066, 2016). "PFOS also significantly stimulates both PPARα and PPARγ, which could also modulate tumor growth." (PMID 27927180, 2016). "These novel data suggest MG-specific PPARγ expression and signaling is critical during breast tumourigenesis, and may serve as a strong candidate predictive biomarker for response of breast cancer patients to the use of therapeutic strategies that include PPARγ ligands." (PMID 25889730, 2015). "Surprisingly, the dominant negative isoform γORF4, till now associated with tumor pathogenesis, is expressed in all analyzed tissues and cell lines, suggesting a not negligible contribute to PPARG activity also in other physiologic and pathological cell processes." (PMID 24790595, 2014). "Moreover, PPARγ has diverse biological functions, such as promoting terminal differentiation of adipocytes, inducing differentiation and apoptosis of tumor cells and inhibiting tumor angiogenesis." (PMID 23939428, 2013). "In addition, we provide results suggestive of bi-directional interaction between FABP4 and PPARγ pathways that may be driving aggressive tumor cell behavior in bone." (PMID 24240026, 2013). "Finally, a large body of evidence supports PPARγ involvement in tumor development." (PMID 22848209, 2012). "The role of PPARγ in other cell types in the tumor microenvironment, however, is largely unknown." (PMID 22934105, 2012).
tumor (continued). "Thus, activation of PPARγ in the tumor microenvironment appears to lead to generation of Tregs and inhibition of host T-cell antitumor activity, resulting in an immunosuppressive environment that promotes tumor progression." (PMID 22934105, 2012). "Indeed, activation of PPARγ in macrophages, Tregs, and NK cells may lead to an immunosuppressive environment that promotes tumor progression." (PMID 22934105, 2012). "PPARγ activation plays a role in diverse physiological and pathophysiological events including stimulation of adipocyte differentiation, activation of insulin, regulation of lipid metabolism, inhibition of tumor cell proliferation, and diverse effects on inflammatory processes." (PMID 22091432, 2011). "Thus, reduction of PPARα and PPARγ expression may be an additional mechanism for facilitating the proinflammatory and tumor-promoting effects of GW501516." (PMID 21318167, 2010). "Target genes that mediate the anticancer activity of the activated PPARγ are still largely undefined and can be related to a wide range of processes including tumour cell differentiation, apoptosis, anti-proliferative effects, and modulation of angiogenic phenotype of the tumour microenvironment." (PMID 19587804, 2009). "Thus it is tempting to suppose that IR gene may be considered a new anticancer target for PPARγ, providing further evidence for the use of TZDs as anti-proliferative agents in selected tumours overexpressing the IR." (PMID 19587804, 2009). "However, more recent evidence wascollected, that PPARγ is a context-specific tumor modulator, whose effector profile iscomplemented and modified by PPARγ-independent effects of its ligands (e.g., TZDs and eicosanoids) and byreciprocal regulation of PPARγ through members of the ERK cascade asfollows." (PMID 18596912, 2008). "PPARγ might also regulate the generation of thecomplex vascular network that supplies tumor cells." (PMID 18704200, 2008). "Therefore, the inhibition of tumor proliferation by PPARγactivators may be explained in part by PPARγ-dependent TGFβ1 repression, supporting the concept that the PPARγ activators may be applied forcontrolling TGFβ1-induced cancer metastasis and fibrosis." (PMID 18615188, 2008). "Thus TZDs inhibit cell proliferation and tumor growth in a PPARγ-independent manner." (PMID 18584037, 2008). "Theeffects of TZDs in cultured cells have been extended to several tumor models inanimals and the results are encouraging.In athymic mice, the growth rates of xenografts of ovarian, thyroid, andbladder cancer are markedly affected by a variety of PPARγ-stimulating agents." (PMID 18670615, 2008). "PPARγ may function as a tumor suppressor duringearly events of carcinogenesis." (PMID 19125177, 2008). "In addition to the question of whether PPARγ is a tumor suppressor orhas tumor-promoting activity in each cancer cell type, the effects of PPARγ on angiogenesis and the immune system must also be considered." (PMID 18509498, 2008). "Besides increasingangiogenesis, increasing PPARγ might be another mechanism that allows tumor cellsto enhance their survival under these unfavorable conditions." (PMID 18784849, 2008). "Genetic and molecular profilingof human cancers may in the future enable selection of a tumor subtypesusceptible to PPARγ agonists, as specific genotypes and patternsof nuclear receptor and cofactor expression might predict resistance orresponsiveness to PPARγ signal transduction." (PMID 19125177, 2008). "Variability in PPARγ-mediated effects on cell proliferation couldarise from tumor heterogeneity in nuclear receptor cross-talk, complement ofcofactors, or mutated or aberrant signaling pathways that override PPARγ signaling, leading to an apparent lack ofeffect of rosiglitazone." (PMID 19125177, 2008). "The authors hypothesized that PPARγ achieved its antagonistic effect by competitively binding to estrogen-responsive elements on promoters of genes which may be required for estrogen-dependent tumor growth." (PMID 17407572, 2007).